ENSG00000261709
Synonyms: LOC124900370
Gene: Small nucleolar RNA gene on chromosome 15 (45,214,906 to 45,215,033, reverse strand). Ensembl gene ENSG00000261709.
Gene Ontology:
Biological process: RNA processing
Cellular component: nucleolus
Homologues: Paralogues in human: SNORA11F (87% identical), SNORA11D (86% identical), SNORA11E (86% identical), SNORA11C (84% identical), SNORA11B (82% identical), SNORA11 (80% identical), SNORA11G (73% identical).